HLA-B (major histocompatibility complex, class I, B)
Diseases named in the same sentence as HLA-B in open-access papers (continued):
Sharing a sentence is not in itself a finding about the gene and the disease.
COVID-19 (87 papers, 2020 to 2025). A disease caused by infection with severe acute respiratory syndrome coronavirus 2. "The HLA-B40 antigen, which initially resulted to be significantly associated to SARS-Cov-2, only exhibited the single allele HLA-B*40:02 in the control group, while in patients it was present with two allelic variants: HLA-B*40:02 and HLA-B*40:01." (PMID 33343579, 2020). "Here, we provide evidence that HLA-B variants associate with COVID-19 severity based on the HLA-B –21 M/T dimorphism." (PMID 39487235, 2025). "Certain HLA-B alleles, including B46:01, have also been associated with increased susceptibility to COVID-19." (PMID 41012626, 2025). "Collectively, these results demonstrate that HLA-B –21 M/M genotypes associate with protection from severe manifestations of COVID-19." (PMID 39487235, 2025). "Together, these data show that genetic variations in HLA-B, which tune NK cell functionality, are associated with COVID-19 severity." (PMID 39487235, 2025). "To study the influence of HLA-B variants on COVID-19 severity, we determined HLA-B alleles in 230 unvaccinated patients who were hospitalized with COVID-19 and required respiratory support during the early stages of the pandemic." (PMID 39487235, 2025). "To investigate the association between the HLA-B –21M/T dimorphism and the clinical severity of COVID-19, we analyzed a cohort of hospitalized patients with primary SARS-CoV-2 infection, who were genotyped for the HLA-B –21M/T dimorphism." (PMID 40650195, 2025). "In the present study, we investigated the role of the HLA-B –21 dimorphism in a cohort of 449 patients hospitalized with COVID-19, aiming to assess its potential influence on the risk of developing severe disease." (PMID 40650195, 2025). "In our study, we analyzed the potential association between the HLA-B –21M/T dimorphism and COVID-19 severity." (PMID 40650195, 2025). "HLA-B*54:01, HLA-B*56:01, and HLA-B*56:04 were associated with COVID-19 patients when compared to Hong Kong Chinese Cord Blood Registry controls (p > 0.05)." (PMID 38667755, 2024). "Our study demonstrated a potentially increased risk of symptomatic COVID-19 in carriers of HLA-B*42:01." (PMID 39768617, 2024). "HLA-B is involved in peptide presentation; its alleles have been associated with COVID-19 and expression levels in human lung cells of SARS-CoV-2-infected individuals." (PMID 38674456, 2024). "We found that the presence of HLA-B*08:01 increased the risk of severe COVID-19 by more than eight times and, additionally, the HLA-B*08:01-C*04:01-DRB1*03:01-DQB1*03:01 haplotype was observed in both of our patients with co-presence of four risk alleles." (PMID 39768617, 2024). "The HLA class I alleles HLA-A*02:01 and HLA-B*40:01, related to high COVID-19 vaccine response, were found, as well as HLA-A*03:01, HLA-B*08:01 HLA-B*18:01, and HLA-C*07:01 related to low vaccine response." (PMID 38637586, 2024). "COVID-19 patients in a Chinese cohort showed HLA-B*51:01 alleles were significantly associated with severe COVID-19." (PMID 38667755, 2024). "HLA-B*39 (p = 0.02) alleles were found more in COVID-19-infected individuals than in healthy individuals; yet, the p-values were insignificant after being adjusted for multiple comparisons." (PMID 38667755, 2024). "We showed that individuals carrying the HLA-B*15 allele have a good Nab response to COVID-19 vaccines, unfortunately, these populations are more susceptible to suffer from Omicron BA.5.2 and XBB.1.16 variant breakthrough infection later." (PMID 39257586, 2024). "In an Italian cohort, carriers of the HLA-B*44 allele had a lower risk of developing severe COVID-19 symptoms; in a Dutch study, the HLA-B*15:03 allele was associated with a reduced risk of infection." (PMID 39684907, 2024). "HLA-B*35 was significantly associated with severe COVID-19 in a study with 92 patients of 15 nationalities from the United Arab Emirates (p = 0.0051)." (PMID 38667755, 2024).
COVID-19 (continued). "Our results highlight that HLA-B mRNA expression levels contribute to COVID-19 severity as well as variation in ethnicities associated with COVID-19." (PMID 38674456, 2024). "In Egypt, a study with 69 COVID-19 patients showed that HLA-B*41 and HLA-B*42 were associated with severe COVID-19." (PMID 38667755, 2024). "In a western Indian population, HLA-B*15 was associated with protection against COVID-19 (p = 0.008), while HLA-B*40 was associated with mild COVID-19 infections (Pc = 0.03)." (PMID 38667755, 2024). "In an Ecuadorian population made up of 52 COVID-19-infected individuals and 87 controls, HLA-B*39 was associated with a risk of COVID-19 development." (PMID 38667755, 2024). "HLA-B*44 alleles were found at a higher incidence in Italians from the north and were positively associated with COVID-19, after multiple regression models." (PMID 38667755, 2024). "For instance, the HLA-B*46:01 variants were demonstrated to influence the susceptibility to severe COVID-19, while the HLA-B*15:03 variant was indicated as a protective one." (PMID 36662838, 2023). "Allele variations in HLA such as HLA-B*46:01 are known to be associated with more severe symptoms of COVID-19 in Asian populations." (PMID 36851358, 2023). "HLA-C*01 and HLA-B*44 are potential molecular determinants in evaluating an individual’s risk of COVID-19, and genotyping of class I and II HLA in COVID-19 patients can identify individuals at a higher risk of a cytokine storm." (PMID 37048725, 2023). "The first study found that HLA-B*44 and HLA-C*01 allele groups were associated with an increased incidence of COVID-19." (PMID 36718139, 2023). "HLA-C*01 and HLA-B*44 are potential molecular determinants for evaluating an individual’s risk of COVID-19." (PMID 37048725, 2023). "Frequency analysis showed that HLA-A*11, HLA-B*38, and HLA-DRB1*14 alleles were significantly associated with severe COVID-19 and HLA-B*52 with mild COVID-19, consistent with some previous studies." (PMID 38301089, 2023). "An interesting trend was noted between the severity of COVID-19 and the HLA-C*04 (P = 0.0077) as well as HLA-B*35 (P = 0.0051) alleles." (PMID 37708194, 2023). "Our results showed that HLA-A*11 and HLA-DRB1*14 alleles were more frequently observed in severe COVID-19 cases, while HLA-B*52 was more common in mild cases, which was in agreement with some previous studies." (PMID 38301089, 2023). "HLA-B*35:01 was reported to be strongly associated with reduced disease duration in mild and moderate COVID-19 in a German population, and the risk effect of HLA-B*51:01 has also been discovered by a GWAS in Chinese COVID-19." (PMID 36849422, 2023). "In another study with 82 patients with COVID-19, a significantly higher frequency of the HLA-C*07:29 and HLA-B*15:27 alleles were found in patients with COVID-19 when compared with healthy individuals." (PMID 35062298, 2022). "In those who had COVID-19, a slightly lower number of alleles was detected for each of the studied HLA loci than in the control group: 15 for HLA-A* (control 17); 22 for HLA-B* (control 33); and 12 for HLA-DRB1* (control 13)." (PMID 36360904, 2022). "Both in vivo and in silico simulation shows that HLA-B*46:01 and HLA-B*54:01 in the Taiwanese population were associated with severe COVID-19, and HLA-B*1301 shows a protective association." (PMID 36366349, 2022). "In contrast, the HLA-B*38 and HLA-C*06 alleles, both analyzed in the same 4 articles (5 studies), were associated with risk for the most severe form of COVID-19 (OR = 1.64, 95% CI 1.03–2.60 and OR = 1.31, 95% CI 1.00–1.72, respectively)." (PMID 35793369, 2022). "Particularly, the relationship between the age and HLA-C*04:01 mirrored the association between advancing age and the severity score of COVID-19, while that of HLA-B*51:01 was in the opposite direction." (PMID 35185875, 2022).
COVID-19 (continued). "We next examined the association of HLA-B*15:01 with asymptomatic infection in the combined UCSF prospective longitudinal COVID-19 Host Immune Response Pathogenesis (CHIRP) and Long-term Impact of Infection with Novel Coronavirus (LIINC) cohorts." (PMID 34031661, 2022). "This observed increase in susceptibility to COVID-19 suggests the HLA-B*15:27 molecule has reduced recognition of an immunodominant COVID-19 viral antigen when compared to controls." (PMID 33910121, 2021). "Particularly, the HLA-B*46:01 and the HLA-B*15:03 variants show the fewest and the greatest predicted binding peptides for COVID-19, respectively." (PMID 33494244, 2021). "On the contrary, HLA-B*14, B*18, and B*49 alleles (more frequent in southern Italy) showed an inverse log-linear correlation with COVID-19 incidence rate, but these associations lost their significance in the multiple regression model." (PMID 33807915, 2021). "HLA-B*46:01 is proposed to be the risk allele of severe COVID-19 infection, and blood group O type is a protective factor of COVID-19." (PMID 33732254, 2021). "After applying a multiple regression model to eliminate confounding factors, only the HLA-C*01 and HLA-B*44 alleles, which are present with a higher frequency in the northern regions of Italy, remained positively associated with COVID-19." (PMID 34344463, 2021). "Another study of Chinese patients with COVID-19 reported that the HLA-A*11:01, HLA-B*51:01 and HLA-C*14:02 alleles were significantly associated with severe disease or worse outcome." (PMID 34344463, 2021). "Each of HLA-A*11:01:01:01 and HLA-C*12:02:02:01 and HLA-B*52:01:01:02 were found to be independently associated with severity of COVID-19." (PMID 33968060, 2021). "In a study investigating COVID-19 positive patients genotyped for HLA loci, HLA-B*15:27 was found to be associated with occurrence of COVID-19 infection (P-value = 0·001 [Fisher's exact test], OR = 3·59, 95% CI = 1·7–7·5)." (PMID 33910121, 2021). "We performed in silico prediction of CD8 + T cell epitopes within the SARS-CoV-2 S1 domain restricted by the HLA class I alleles of the immunosuppressed COVID-19 patient (HLA-A*02:01, HLA-A*03:01, HLA-B*51:01, HLA-B*56:01)." (PMID 34737266, 2021). "Equally interesting is the study that reported the distribution of HLA allele frequencies in 82 Chinese individuals with COVID-19 and identified HLA-C*07:29 and HLA-B*15:27 and HLA-B as statistically significant." (PMID 34344463, 2021). "In Africa, the lower fatality rate of COVID-19 has been linked to the prevalence of different HLA alleles including the HLA-B*46:01 and HLA-B*15:03." (PMID 33901167, 2021). "By univariate analysis we found that HLA-A*25, B*08, B*44, B*15:01, B*51, and C*01, and C*03 alleles showed a positive correlation with COVID-19 incidence rate, whereas HLA-B*14, B*18, and B*49 showed an opposite trend." (PMID 32717807, 2020). "According to the results, the prevalence of the HLA-C*01 and HLA-B*44 alleles are predictive of the incidence of COVID-19 in the different Italian regions and therefore confer susceptibility to SARS-CoV-2 infection." (PMID 33343579, 2020). "In our study, two additional class I alleles group were associated with COVID-19 severity: HLA-B*37 emerged as a potential protective factor against severe and critical cases, whereas HLA-B*49 was identified as a possible risk factor specifically for critical cases." (PMID 40508150, 2025). "NKG2A+ NK cells have been reported to recognize SARS-CoV-2-infected cells, but it remains unclear whether the HLA-B –21 M/T dimorphism associates with COVID-19 severity." (PMID 39487235, 2025). "Previous studies have reported associations of HLA-B alleles with COVID-19." (PMID 39487235, 2025). "To investigate how the HLA-B –21 M/T dimorphism might impact the severity of COVID-19, we analyzed the HLA-B alleles in a group of 449 patients hospitalized between April 2020 and January 2021." (PMID 40650195, 2025).
COVID-19 (continued). "In the comparative analysis between severe and critical COVID-19 patients, two HLA class I allelic groups initially showed associations: HLA-B*08 appeared to act as a potential protective factor against progression to critical illness, while HLA-B*50 was associated with an increased risk." (PMID 40508150, 2025). "HLA-B*37:01 was associated with deceased COVID-19 individuals (p = 0.0331); therefore, it might be involved in severe COVID-19 disease outcomes." (PMID 38667755, 2024). "Moreover, we demonstrated that the severe symptomatic course of COVID-19 can be associated with the presence of HLA-B*08:01, C*04:01, DRB1*03:01, and DQB1*03:01, while HLA-DRB1*08:01 appeared to be protective against severe COVID-19 disease." (PMID 39768617, 2024). "HLA-B*08:01 and HLA-B*08 correlated with raised COVID-19 risk and mortality." (PMID 38667755, 2024). "Moreover, we have demonstrated that the severe course of COVID-19 can be associated with the presence of HLA-B*08:01, C*04:01, DRB1*03:01, and DQB1*03:01, while HLA-DRB1*08:01 appears to be protective." (PMID 39768617, 2024). "Nevertheless, due to strong linkage disequilibrium, both HLA-B*35:01 and C*04:01 may be considered to be associated with the severe course of COVID-19, and some inflammatory mechanisms can be common in COVID-19 and SAT." (PMID 39768617, 2024). "In Spain, HLA-B*14:02 was associated with a reduced risk of COVID-19 (p = 0.006)." (PMID 38667755, 2024). "Similarly, HLA-B*35 was more significantly associated with mild than severe COVID-19 in a South Asian population." (PMID 38667755, 2024). "We found that HLA-A*11 and HLA-DRB1*14 alleles may be susceptibility factors for severe COVID-19, while HLA-B*52 may be a protective factor." (PMID 38301089, 2023). "We wondered whether different peptide binding preferences account for the association of certain HLA-B alleles with COVID-19 susceptibility." (PMID 36849422, 2023). "The HLA-B*52 allele had a significantly higher frequency in the mild group compared to the hospitalized group (OR 0.2, 95% CI 0.06–0.6, P = 0.006); carrying this allele appears to be protective against severe COVID-19." (PMID 38301089, 2023). "We compared HLA-B allele frequencies in COVID-19 patients and controls." (PMID 36849422, 2023). "Furthermore, a study in China showed that HLA-C*07:29 and HLA-B*15:27 were more frequently present in COVID-19 patients; however, these alleles are rare in the Chinese population." (PMID 35745684, 2022). "For example, HLA-B*46:01 may be particularly vulnerable to COVID-19; however, we found that hiPSC-CMs with this allele (THTC-02, THTC-10, and THTC-13) were not significantly higher in SARS-CoV-2 infections." (PMID 35745684, 2022). "Regarding the specific association of HLA alleles with COVID-19, healthy individuals carrying HLA-B*44 and/or -C*01 (group C1) may be more susceptible to be infected with SARS-CoV-2 and to spread the infection within the population." (PMID 35960731, 2022). "Notably, HLA-B*51:01 is one of the alleles belonging to the HLA-B07 supertype and was also shown to be more frequently carried by patients with severe COVID-19." (PMID 35681490, 2022). "Our results revealed that the hiPSC-CM line THTC-09 (HLA-A*33:03, HLA-B*58:01, HLA-C*03:02, and HLA-DRB1*03:01) was more susceptible to SAR-CoV-2 infection which correlated with the high level of ACE2 receptor expression." (PMID 35745684, 2022). "Individuals with the HLA-B*46:01 allele could be especially vulnerable to COVID-19, as with SARS, since this allele has the fewest possible binding peptides for SARS-CoV-2." (PMID 33901167, 2021). "On the other hand, the allele with the least number of predicted clusters in our analysis was HLA-B*51:01, which could suggest an increased susceptibility to COVID-19." (PMID 35095907, 2021). "Although HLA-C, had the greatest antigenic peptide capacity from SARS-CoV-2, HLA-B and HLA-A, could be more relevant based on COVID-19 risk of infection in LATAM countries." (PMID 34205992, 2021).
COVID-19 (continued). "In conclusion, it would be expected that pandemic COVID-19 and the vaccination against this pathogen could significantly increase ADs, particularly those associated with HLA-B*08:01, HLA-A*024:02, HLA-A*11:01, and HLA-B*27:05." (PMID 34447375, 2021). "The HLA-B*46:01 allele has a low binding affinity, suggesting that subjects with this allele may have a higher risk of developing the more severe forms of COVID-19, as previously shown with SARS-CoV." (PMID 34344463, 2021). "The HLA-A*24:02 allele was also involved in a study on bronchoalveolar lavage fluid and blood samples of COVID-19 patients, while the HLA-A*11:01 allele, together with the HLA-A*02:06 and HLA-B*54:01 alleles, could protect against infection." (PMID 34344463, 2021). "In terms of SARS-CoV-2, an in silico study has found that individuals with HLA-B*46:01 variants may be susceptible to COVID-19, whereas HLA-B*15:03 represents a protective variant since it could provide T-cell based immunity." (PMID 33396584, 2020). "The fewest predicted binding peptides for SARS-CoV-2 were found for HLA-B*46:01, suggesting that individuals harboring this allele may be particularly vulnerable to COVID-19, as previously shown for SARS-CoV-1." (PMID 33092637, 2020). "However, whether the HLA-B –21 dimorphism affects the risk of developing severe COVID-19 remains unclear." (PMID 39487235, 2025). "However, HLA-B*14, HLA-B*18, and HLA-B*49 were inversely associated with COVID-19." (PMID 38667755, 2024). "In addition, comorbidities are associated with COVID-19 and HLA-B expression levels." (PMID 38674456, 2024). "The presence of specific HLA-B alleles has been associated with increased susceptibility to different viral infections and therefore, it may be considered a potential predictive biomarker of COVID-19 severity." (PMID 35960731, 2022). "HLA-B*15:03 also presented peptides shared among human coronaviruses and might signal that this gene variation may confer T-cell-mediated protection against not only COVID-19 but other coronaviruses that cause SARS or MERS as well." (PMID 35632439, 2022). "Besides, the HLA-B*38 and HLA-C*06 alleles were associated with risk for severe COVID-19." (PMID 35793369, 2022). "Therefore, patients carrying the first variant may be particularly susceptible to COVID-19; in contrast, patients carrying the HLA-B*15:03 variant may have some protection." (PMID 33494244, 2021). "The HLA-B*27:07 allele was detected in Italian individuals with a severe manifestation of COVID-19 and also identified in India, Colombia, Spain, and South Africa but not in populations from Asia and Oceania (countries that are less affected by COVID-19) and Brazil." (PMID 33824725, 2021). "It has been shown that the HLA-B*46:01 allele has a low degree of binding affinity, suggesting that subjects with this allele may have a higher risk of developing the more severe forms of COVID-19." (PMID 33343579, 2020). "Specific gene variants, including those within the HLA-DRB, HLA-B, and ABO blood group systems, have been linked to varying degrees of susceptibility and severity of COVID-19." (PMID 41012626, 2025). "Given that the HLA-B –21 dimorphism affects HLA-E surface expression and NK cell education, further research is warranted to explore its potential role not only in COVID-19 but also in other infectious diseases." (PMID 40650195, 2025). "Here, we show that rare HLA-B –21 M/M genotypes are enriched in patients with moderate COVID-19 and depleted in patients with severe manifestations." (PMID 39487235, 2025). "In this study, we provide evidence that patients with HLA-B –21 M/M genotypes follow less severe COVID-19 disease trajectories." (PMID 39487235, 2025). "We assessed HLA-B*15:01-expressing COVID-19 patients across the disease severity spectrum, from asymptomatic and mild infections, to hospitalized moderate and severe/critical patients, as well as prepandemic unexposed individuals." (PMID 40892914, 2025).